IL2 (interleukin 2)
Diseases named in the same sentence as IL2 in open-access papers (continued):
Sharing a sentence is not in itself a finding about the gene and the disease.
tumor (continued). "It has been reported that the expansion and cytotoxicity of PBMC-derived NK cells following IL-2 stimulation were deficient in dogs with neoplasms compared to healthy dogs." (PMID 38668417, 2024). "The low‐risk subgroup had higher tumor mutation burden and activation of IL2/STAT5, IL2/STAT3 and IFN‐gamma response pathways." (PMID 38017652, 2024). "These linkers are preferentially cleaved by tumor-associated proteases, releasing fully active, WT IL-2 in the tumor from the otherwise inactive prodrug." (PMID 39114660, 2024). "The validity of IL-2 therapy in increasing life expectancy cannot be associated with all tumor types." (PMID 38893211, 2024). "These nanoparticles can modify CAR-T cells in vivo, regulate CD4+ T cell function, inhibit the expression of tumor-associated immunosuppressive cells, and control the release of immunosuppressive agents like IL-2 and transforming growth factor-β (TGF-β)." (PMID 39397869, 2024). "Together, these results indicate that loss of MCJ in IL2-expanded TCR-specific CD8 cells can enhance their antigen-specific anti-tumor-killing activity in vitro by promoting the secretion of IFNγ and their cytotoxic activity." (PMID 38789421, 2024). "A conditionally active IL-2 mimic can be achieved by fusing Neo2A and Neo2B with tumor-associated antigen-binding proteins, such as nanobodies." (PMID 39169031, 2024). "Because of persistent tumor cells, CD8 + TILs lose their ability to produce triple cytokines TNFα, IL-2, and IFNΥ responsible for showing the PD-1-Tim-3 + phenotype, an effector memory subset causing tumor rejection." (PMID 39692821, 2024). "While our exploratory analysis found significant associations between IL-1B and IL-2 and lymphocyte infiltration, there is a need for additional mechanistic study to exploit the inflammatory axis to induce immune response to tumor." (PMID 38346068, 2024). "Biased IL-2 variants had been discovered to eliminate Treg activation or enhance the tumor specific T cell cytotoxicity." (PMID 38638426, 2024). "In our cohort, it was observed that higher pre-treatment levels of IL-2 and IL-15 were associated with more aggressive tumor behavior and worse outcomes: patients survived less and had lower PFS." (PMID 39199571, 2024). "The intrapleural injection of IL-2 has been reported effective in reducing tumour-associated malignant pleurisy; the level of CEA decreased in MPE patients treated with IL-2, suggesting that the MPE malignancy was reduced after treatment." (PMID 38475858, 2024). "Conversely, increased abundance of lauric acid, IL-1β, and IL-2 in the Fit phenotype was observed, which have been previously implicated in tumor suppression and anti-tumor immunity." (PMID 39575261, 2024). "Fusion with antibodies targeting fibroblast activation protein (FAP) and carcinoembryonic antigen (CEA) can enhance their tumor-targeting capabilities and mitigate cytotoxicity caused by IL-2 retention in peripheral blood." (PMID 39221244, 2024). "Upon comparing our results with their study, we observed that engineered bacteriophages exhibited cytotoxicity as effectively as the gene electrotransfer (GET) of plasmids encoding IL-2 and IL-12, albeit in a different tumor model." (PMID 38400008, 2024). "In HSV vectors, encoding immunomodulatory cytokines like IL-2, IL-12, and GM-CSF enhances tumor regression mediated by CD4+ and CD8+ lymphocytes." (PMID 38731910, 2024). "and activated the expression of factors secreted by tumor cells, which cause immunostimulation, IL2." (PMID 39861845, 2024). "Simlukafusp alfa, a fusion protein, combines fibroblast activation protein (FAP) targeting with interleukin-2 variant (IL2v), focusing primarily on modifying the tumor microenvironment." (PMID 38558814, 2024). "Upon engagement of tumor cells by exogenous IL-15, we detected the association of IL-15Rα with the IL-2/IL-15Rβ and IL-2Rγ chains." (PMID 38637902, 2024).
tumor (continued). "The IC used here is an engineered fusion protein consisting of a tumor-specific monoclonal antibody targeting disialoganglioside (GD2) linked to IL2." (PMID 38077403, 2023). "CD39+ expression has been correlated with tumor-specific recognition and is associated with reduced IFNγ and IL2 expression." (PMID 36689623, 2023). "In a tumour setting, T cells become exhausted due to chronic antigen exposure leading to reduced effector function [loss of interleukin-2 (IL-2), tumour necrosis factor alpha (TNF-α) and Interferon-gamma (IFN-γ) production]." (PMID 37554723, 2023). "The anti-tumour efficacy of 11B12-1 was subsequently validated in a combination with an oncolytic adenovirus encoding IL-2 and TNFα (TILT-123)." (PMID 36817448, 2023). "Long-term stimulation by tumor antigens can cause T cells to gradually lose their original ability to recognize antigens, activate and proliferate, or secrete interleukin-2, leading to T cell depletion." (PMID 37070077, 2023). "IL-2, IFNg, and IL-1 have canonically been associated with a Th1 response and good prognosis, although this can vary depending on the tumor type." (PMID 37104271, 2023). "Tumor-infiltrating lymphocyte immunotherapy (TIL) is an adoptive cell transfer variant where tumor-infiltrating lymphocytes extracted from a metastatic melanoma tumor are cultured with IL-2, which serves to activate T-cells." (PMID 37600918, 2023). "Tumor-associated macrophages (TAMs), matrix metalloproteinases, interleukin-2 (IL-2) and TGF-β present in the microenvironment are the key factors involved in lymphatic dissemination." (PMID 36905477, 2023). "We therefore evaluated T‐cell activation by measuring the levels of interferon‐γ (IFN‐γ) and interleukin 2 (IL‐2) in tumor tissues using an enzyme‐linked immunosorbent assay (ELISA)." (PMID 36684090, 2023). "Our findings define the underlying mechanisms on how IL-2 combined with PD-1 blockade can be synergistic in tumor immunotherapy." (PMID 37932447, 2023). "One example is the introduction of genes encoding immunostimulatory cytokines, such as interleukin 2 and interleukin 12, which stimulate immune cells in tumours." (PMID 37629081, 2023). "The proposed mechanism of action of this drug is that it targets IL-2 to FAP expressing tumor stroma, thereby limiting on-target, off-site toxicities associated with IL-2 cytokine therapy." (PMID 38196606, 2023). "To address dose-limiting toxicity, we treated tumor-bearing mice with variants of IL-2 and IL-12 that were skewed toward T cells expressing CD25 and interleukin 12 receptor subunit beta 1 (Il12rb1), respectively." (PMID 37669107, 2023). "Multivariate analysis showed that IFN-γ, IL-2, and lymphocyte-attracting chemokines increased within tumor cells in the presence of TILs, demonstrating a meaningful association with delayed tumor cell recurrence or death." (PMID 36674491, 2023). "For example, IL-2 has been shown to regulate cell proliferation, apoptosis, and angiogenesis, while IL-2R has been implicated in tumor growth, metastasis, and immune evasion." (PMID 37516849, 2023). "We observed that CD4+ and CD8+ T cell populations both exhibited increased secretion of interferon (IFN)-γ, tumor necrosis factor (TNF)-α, and interleukin (IL)-2, which are associated with anti-tumor activities." (PMID 36915911, 2023). "PD-1/PD-L1 blockade (alone and in combination therapies) restored IL-2 production by tumor-infiltrating T cells which was associated with tumor inhibition." (PMID 37189417, 2023). "Lachnospiraceae_NK4A136 genus is considered as intestinal probiotics due to its positive association with intestinal barrier-related factors, anti-tumor immune factors (IL-2, INF-g, and NK cells) and anti-inflammatory response." (PMID 36597142, 2023). "IL-2 has been found to stimulate Tregs, with some studies associating it with tumour growth and progression, while others suggest its potential anti-tumour activity." (PMID 38137361, 2023).
tumor (continued). "We have previously demonstrated that an adenovirus encoding a human variant IL-2 was capable of counteracting tumor immunosuppression in a hamster pancreatic model as a monotherapy." (PMID 37949944, 2023). "Tumor-selective IL-2 prodrugs have also recently attracted considerable interest from different research groups for the purpose of increasing intratumoral IL-2 abundance and reducing toxic side effects caused by systemic administration via injection." (PMID 37483629, 2023). "The expression of IL-2 following tumor antigen exposure in CD8+ T cells has been associated with longer-surviving and more potent CAR-T cells." (PMID 36720856, 2023). "In the B16.F10 murine melanoma model, combined treatment of tumors using IL-2 encoding plasmid (pIL-2) and IL-12 encoding plasmid (pIL-12) induced significant tumor growth delay and 71% complete tumor regression." (PMID 36428682, 2022). "The same treatment caused IL-2 serum levels boosting (578 pg/ml) compared with untreated tumor-bearing mice that exhibited values of 185, 107, 30, and 52 pg/ml for IL-2, IL-4, IL-10, and IFN-γ, respectively." (PMID 35845806, 2022). "RO6874281 is an immunocytokine consisting of an interleukin-2 variant targeting fibroblast activation protein-α, which is greatly upregulated in remodelling tissues such as tumours." (PMID 35804943, 2022). "Then, bufalin-induced upregulation of the M1-like TAMs stimulated the Th1 cell proliferation and Th1-associated anti-tumor cytokines (IL-2 and IFN-γ) accumulation, while decreasing the proportion of Th2 and its pro-tumor cytokines (IL-4 and IL-13) in the TME." (PMID 36615387, 2022). "We also found that knocking out ALKBH5 activates the immune system with more antitumor-associated cytokines (IFN-γ, IL-2) and fewer pro-tumor-associated cytokines (IL-10, IL-13)." (PMID 36566230, 2022). "T cells exhaustion, defined by the progressive loss of effector function after persistent infection or tumor antigens, lose the ability to produce cytokines, such as IFNγ, TNFα, and IL-2." (PMID 36050760, 2022). "When tumor bearing mice were treated with Salmonella + Alb-IL2, we observed increased frequencies of intra-tumoral CD4 and CD8 T cells as well as elevated levels of pro-inflammatory cytokines (IFNγ, TNFα, IL-2) in the tumor associated CD8 T cells." (PMID 35962391, 2022). "The prodrug of IL-2 is selectively activated in the tumor microenvironment with tumor-associated enzymes." (PMID 35062731, 2022). "In a 2020 article, it was reported that TNF-α can be used as a prognostic indicator, while various ILs (IL-2, IL-1β, and IL-6) were also discovered to be linked to tumor prognosis." (PMID 35677632, 2022). "Efforts have been made to improve the anti-tumor activity of IL-2-based therapy and to reduce the associated toxicities." (PMID 36230766, 2022). "Authors have shown interaction between LAG3 and its receptor FGL1 can cause changes in the tumour microenvironment, such as reduction in IL-2 levels, disrupting anti-tumour immunity." (PMID 35625783, 2022). "We also proved Salmonella + Alb-IL2’s ability to exert tumor control in the TC-1 tumors, a murine model of HPV-associated cancer." (PMID 35962391, 2022). "IL-2 at low doses causes the Treg population to expand, which dampens the overall anti-tumor effect and enhances peripheral tolerance." (PMID 35806311, 2022). "The antibody-based delivery of IL-2 to extracellular targets expressed in the easily accessible tumor-associated vasculature showed therapeutic potential for acute myeloid leukemia and other solid tumors." (PMID 35209102, 2022). "IL-2 plays a crucial role in motivating expansion, differentiation, and function of effector T cells, and the loss or downward responsiveness of IL-2 are responsible for the exhausted phenotype in anti-tumor immunity." (PMID 35433427, 2022).
tumor (continued). "Immunocytokines, in which IL-2 is linked to an antibody that targets tumor associated-antigens, have been efficacious in preclinical models and are currently being used in IL-2 based therapy trials." (PMID 35529882, 2022). "Although an oversimplification, for charting purposes, the cytokines were split into three groups by their generalized tumor-destroying (IFN-γ, IL-2, and IL-5), tumor-promoting (IL-10 and IL-4), or SIRS-associated (IL-1β, IL-6, CXCL-1, and TNF-α) properties." (PMID 35465347, 2022). "The anti-tumour efficacy of adenovirus coding for an IL-2 variant (vIL-2) protein—Ad5/3-E2F-d24-vIL2 was evaluated in immunocompetent hamsters bearing pancreatic tumours." (PMID 36140243, 2022). "Numerous IL-2 immunocytokines have been developed to target tumor-associated antigens expressed by cancer cells and their surrounding tissue." (PMID 35104808, 2022). "Our model essentially relies on i.v. engraftment of PBMC isolated from patients with high tumor burden associated to a weekly supply of IL2 and IL7 cytokines." (PMID 36230895, 2022). "Antibodies fused with IL2 directed against tumor-associated antigens have been tested in preclinical models with promising results." (PMID 35799600, 2022). "IL-2 is associated with tumor inhibiting properties by the modulation of lymphocyte proliferation and function." (PMID 35740542, 2022). "This notion was further backed by the continuously increased expressions of IL2, TNFα/β and IFNγ in tumor-associated CD8+ T cell in BAY-I and BAY-I withdrawal groups." (PMID 35013322, 2022). "Effective anti-tumor responses are induced by vaccinia viruses that encode exogenous IL-2 against an orthotopic murine model of HNSCC." (PMID 35740551, 2022). "The results showed CRCs harboring CSF1R c.1085 A>G variant had higher CD40LG and IL-2 expression in tumor tissues than those with CSF1R c.1085 genotype A_A." (PMID 34830445, 2021). "While this is a reasonable strategy to avoid off-tumor side effects, clinical benefit has been seen with multiple untargeted IL-2 variant molecules such as NKTR-214, THOR-707, and ALKS-423023,24,54,57." (PMID 34011961, 2021). "As this population can recover function after culturing in the presence of IL-2, their presence is associated with an enhanced tumor reactivity." (PMID 34885176, 2021). "From the immunotherapeutic perspective, the main caveats associated with the use of systemic recombinant IL-2 therapy relate to low therapeutic levels in the tumor microenvironment (TME) and the activation of immunosuppressive cells, such as TRegs." (PMID 34084172, 2021). "Increased numbers of FOXP3+ lymphocytes, higher IL17A, lower IL2 and a principal component involving Ki67 and macrophages were independently associated with worse outcome in the tumor compartment." (PMID 33648463, 2021). "We mask the activity of a CD8 T cell-preferential IL-2 mutein/Fc fusion protein with IL2 receptor beta linked to a tumor-associated protease substrate." (PMID 33986267, 2021). "One of the significant challenges in using IL-2 in cancer treatment is the activation of Tregs because these cells consume IL-2 and are unable to produce it themselves, suppressing anti-tumor responses and causing tumor growth and progression." (PMID 34868907, 2021). "In brief, the shift from a Th1 to a Th2 inflammatory response will lead to an increase in immunosuppressive cytokine release (IL-2, IL-4, IL-7, IL-13, and IL-15) by neoplastic elements and tumor-associated cells, sustaining tumor growth and spread." (PMID 34685762, 2021). "In 1986, Rosenberg and colleagues described the cytotoxic potential of IL-2 expanded tumor-infiltrating lymphocytes (TILs), recognizing tumor-associated antigens from resected tumors in mice." (PMID 33807011, 2021). "This methodology allows for the incorporation of tumor associated antigens onto the surface of BMDCs, which are then used as an envelope for IL-2-loaded PLGA NP." (PMID 34359665, 2021).
tumor (continued). "For example, the combination of a tumor-targeted antibody with IL2-Fc (bearing D265A mutation to abolish Fc effector function) treatment had superior tumor control, mediated by CD8+T cells, NK cells, macrophages, and polymorphonuclear cells." (PMID 34790830, 2021). "The IL-2 variant RNA-LNP proved effective in syngeneic mouse tumor models, and the anti-tumor effect was significantly enhanced in combination with RNA-LPX vaccination or PD-1/PD-L1 checkpoint inhibition." (PMID 33858437, 2021). "We engineered and generated a unique IL-2 prodrug that combines a potent CD8 T cell-preferential IL-2 mutein with a blocking IL-2 receptor that can be released by tumor-associated MMPs." (PMID 33986267, 2021). "Checkpoint inhibitors antagonistic for PD-L1 have exhibited increased survival and tumor control when combined with a decreased affinity IL-2-variant immunocytokine that targets CEA." (PMID 33803078, 2021). "CD4 T lymphocytes evolving in a tumor environment rich in IL-2 (in association with TGFβ) express the transcription factor Foxp3, which impairs the differentiation of Tregs and the production of IL-10, that participate in an immunosuppressive microenvironment." (PMID 33498483, 2021). "To allow IL-2 to preferentially target tumor-infiltrating lymphocytes (TILs) with long half-life, we designed ProIL2 to have four domains: human IgG1, an IL-2 variant, an IL-2 receptor, and a flexible MMP-cleavable linker." (PMID 33986267, 2021). "While IL2 is a cytokine that has a positive role in immune activation by activating NK cells and CTLs to cause tumor regression." (PMID 34692696, 2021). "We used the well-studied CpDV-IL2-sPD1/MS DNA vaccine, which encodes two tumor antigens, MUC1 (M) and survivin (S), and included soluble PD1, CpG motif, and IL-2 as immunoadjuvants to enhance the CD8+ T cell-mediated antitumor immune response." (PMID 34950581, 2021). "The high expression level genotype +114 TT was associated with a lower risk of HCC development in a hepatitis B positive cohort, while high peritumoral IL-2 levels were associated with a lower risk of tumor recurrence." (PMID 34025657, 2021). "More precisely, we used a targeted version of IL2 genetically fused to the antibody F8, specific for the tumor-associated antigen Extra Domain A of fibronectin." (PMID 33796916, 2021). "For instance, IL-2, IL-15, and IL-21 are reported to promote tumor suppression in melanoma, whereas IL-1, IL-4, and IL-6 are associated with tumor progression in breast, prostate, and lung cancer." (PMID 33800170, 2021). "Modifications made in the IL-2 receptor-binding structure leads to preferential binding of IL-2 variant cytokine to receptors on effector anti-tumor lymphocytes over T regulatory (TReg) cells." (PMID 34084172, 2021). "While administration of TILs with IL-2 demonstrated the specific and high cytotoxic potential of the immune cell product against the designated tumor, the application of IL-2 caused toxic side effects." (PMID 33807011, 2021). "Two IV injections of ex vivo IL-2-activated NK cells combined with an anti-PD-1 antibody caused a significant tumor growth delay." (PMID 34588986, 2021). "After immunization using CD40L-EXO in mice, the increased production of anti-tumor-associated cytokines, including IL-2 and IFN-γ, were observed." (PMID 34576180, 2021). "The measles virus Schwarz strain (MeVac) vector encoding with IL-2 has shown more immune activation, and MeVac with FmIL-15 promoted NK and T cell infiltration in mouse tumor models." (PMID 33266177, 2020). "It was suggested that increased IL-2 production by murine PTPN22 deficient T cells helped them overcome the suppressive effects of TGFβ in the tumor microenvironment." (PMID 33425916, 2020). "Surprisingly, however, such variants are less effective than wild-type IL-2-Fc in mediating tumor rejection, since Fc-mediated immune effector functions appear to be required for Treg elimination." (PMID 32917054, 2020).